RB1-DT (RB1 divergent transcript)
Synonyms: ncRNA-RB1; LINC00441
Gene: Long non-coding RNA gene on chromosome 13 (48,291,549 to 48,303,723, reverse strand). Ensembl gene ENSG00000231473.
Diseases named in the same sentence as RB1-DT in open-access papers:
RB1-DT is named in the same sentence as 5 diseases in open-access papers, as found by Europe PMC text mining. Sharing a sentence is not in itself a finding about the gene and the disease.
RB1-DT shares sentences with these, for which no sentence is quoted: tumor (3 papers); cancer (2); gastric cancer (2); hepatocellular carcinoma (2); cervical cancer (1).